GDF10 (growth differentiation factor 10)
Description:
Growth factor involved in osteogenesis and adipogenesis. Plays an inhibitory role in the process of osteoblast differentiation via SMAD2/3 pathway. Plays an inhibitory role in the process of adipogenesis.
Synonyms: BMP-3B; BIP; BMP3B
Tractability: Antibody: UniProt places it where antibodies can reach, with medium confidence; UniProt predicts a signal peptide or a membrane-spanning region; its Gene Ontology location is reachable by antibodies, with medium confidence.
Gene: Protein-coding gene on chromosome 10 (47,300,171 to 47,313,577, forward strand). Ensembl gene ENSG00000266524.
Subcellular location: Secreted
Subcellular location (Human Protein Atlas): Vesicles; Predicted to be secreted
Gene Ontology:
Molecular function: cytokine activity; growth factor activity
Biological process: negative regulation of ossification; cell surface receptor protein serine/threonine kinase signaling pathway; positive regulation of osteoblast differentiation; skeletal system development; transforming growth factor beta receptor signaling pathway; fat cell differentiation; osteoblast differentiation
Cellular component: extracellular matrix; extracellular region
Genetic constraint (gnomAD): Loss-of-function variants: 23 observed, 29.27 expected, observed/expected ratio (o/e) 0.79, 90% interval 0.56 to 1.11. The upper end of that interval is the gene's LOEUF score, 1.11, which puts it in group 4 of 6, group 1 being the genes least tolerant of losing a copy. Missense variants: 764 observed, 652.8 expected, observed/expected ratio (o/e) 1.17, 90% interval 1.1 to 1.24. Synonymous variants: 327 observed, 291.29 expected, observed/expected ratio (o/e) 1.12, 90% interval 1.02 to 1.23.
Homologues: Orthologues: chimpanzee GDF10 (99% identical), macaque GDF10 (96% identical), pig GDF10 (87% identical), rat Gdf10 (83% identical), mouse Gdf10 (83% identical), guinea pig GDF10 (82% identical), rabbit GDF10 (76% identical), zebrafish gdf10a (50% identical), tropical clawed frog gdf10 (46% identical), zebrafish gdf10b (42% identical). Paralogues in human: BMP3 (42% identical), BMP2 (20% identical), BMP4 (20% identical), GDF5 (19% identical), GDF6 (19% identical), BMP6 (18% identical), BMP8A (18% identical), BMP8B (18% identical), GDF2 (18% identical), BMP5 (18% identical), GDF7 (18% identical), GDF1 (17% identical), and 19 more.
Diseases named in the same sentence as GDF10 in open-access papers:
GDF10 is named in the same sentence as 54 diseases in open-access papers, as found by Europe PMC text mining. Sharing a sentence is not in itself a finding about the gene and the disease. The quoted sentences say what the papers report.
lung carcinoma (12 papers, 2005 to 2025). "Conversely, GDF10 expression silence reversed these effects, and GDF10 is regarded as a tumor growth inhibitor and a silenced gene in lung cancers." (PMID 38602568, 2024). "delineated that GDF10 expression is suppressed in lung cancer, and that the aberrant downregulation of GDF10 contributes to the tumor growth in the lung." (PMID 33407592, 2021). "In an independent external sequencing sample cohort, these genes also performed impressively, with the AUC value for CBLC at 0.800, while the AUC values for FABP4, GDF10, and LTBP4 all reached 1.000, further validating their potential as diagnostic markers for lung cancer." (PMID 40766337, 2025). "In the TCGA cohort, the AUC values ​​of CBLC, FABP4, GDF10, and LTBP4 genes were 0.982, 0.997, 0.980, and 0.983, respectively, indicating that these genes have a high diagnostic efficiency in distinguishing lung cancer samples from normal control groups." (PMID 40766337, 2025). "Interestingly, Tandon and colleagues demonstrated that there also exists an inverse relationship between RUNX2 and GDF10 expression in lung cancer cells." (PMID 39307303, 2024). "Moreover, the predicted target of miR-587 in this study, GDF10, also known as BMP3B, belongs to the transforming growth factor-β (TGF-β) family, which has been indicated as a tumor suppressor in lung cancer and also a factor in the progression of PCa." (PMID 33407592, 2021). "For other IRGs, such as LGR4, GDF10, GREM1, IL20RB, INHA, VIPR1, and ADM2, they had been verified to participate in carcinogenesis and affect patients’ prognoses in other cancers, although the relevant studies were rare in lung cancer." (PMID 33386920, 2021). "The transforming growth factor β (TGF-β) family member bone morphogenetic protein-3B (BMP-3B/GDF10) is regarded as a tumor growth inhibitor and a gene silenced in lung cancers; however the regulatory mechanisms leading to its silencing have not been identified." (PMID 22537242, 2012). "Moreover, RUNX2 could recruit histone H3K9-specific methyltransferase Suv39h1 to BMP3B (GDF10) proximal promoter and then suppress the BMP3B expression, which is regarded as a tumor growth inhibitor and a gene silenced in lung cancers." (PMID 38049682, 2023).
prostate carcinoma (10 papers, 2012 to 2025). A carcinoma that arises from epithelial cells of the prostate gland. "It has been shown that osteoblasts secrete growth differentiation factor 10 (GDF10) and TGFβ2, factors that induce quiescence of prostate cancer cells activating the p38MAPK/T252RB pathway." (PMID 38203403, 2023). "Bone secretes factors such as TGFβ2, GDF10, and others, which induce cellular quiescence and dormancy in some prostate cancer cell lines." (PMID 37464317, 2023). "For example, PGM5-AS1 upregulates GDF10 gene expression by competitively binding to miR-587, inhibiting prostate cancer cell growth and accelerating apoptosis." (PMID 34249715, 2021). "TGFβ2 and GDF10 can promote cell cycle arrest by binding to the TGF-βRIII receptor expressed by prostate cancer cells." (PMID 31817646, 2019). "Differentiated osteoblasts located around the tumor cells in the bone induced dormancy in prostate cancer cells by secreting proteins including growth differentiation factor 10 (GDF10) and TGFβ2." (PMID 31817646, 2019). "Moreover, murine models of metastatic prostate cancer have shown osteoblast secreted TGFb2 and GDF10 are key to promoting cellular quiescence and maintaining tumour dormancy in the bone." (PMID 37608096, 2023). "Furthermore, Yu-Lee and colleagues recently identified the osteoblast-derived factors GDF10 and TGF-beta 2 as a means by which prostate cancer cells are induced into a dormant state in bone." (PMID 29867053, 2018).
Stroke (9 papers, 2017 to 2024). Sudden impairment of blood flow to a part of the brain due to occlusion or rupture of an artery to the brain. "In the post stroke axonal sprouting transcriptome, GDF10 is one of the most highly upregulated genes during the initiation of axonal sprouting in peri-infarct cortical neurons." (PMID 35723585, 2022). "GDF10 administration increased axonal sprouting in the adult and enhanced functional recovery from stroke." (PMID 33479258, 2021). "GDF10 is considered a stroke-induced signal that promotes axonal outgrowth and enhanced functional recovery after stroke." (PMID 32943671, 2020). "GDF10 is a TGF beta superfamily member that is induced in the peri-infarct region in stroke." (PMID 33479258, 2021). "Moreover, GDF10 has been recently reported to be a signal for axonal sprouting and neuron functional recovery after stroke." (PMID 29244816, 2017). "Notably, analysis of 341 DE mRNA associated with stroke (259 upregulated, 82 downregulated) in the IR group revealed upregulation of genes like Ccl2, Cxcl1, C3, Serpine1, Adamts7, Csf3, Ptx3, MMP8, Lif, and Lcn2, and downregulation of Gdf10, Agtr2 and Shank3." (PMID 39170713, 2024). "Gdf10 is also expressed by adult brain ECs and promotes astrocyte and neuronal survival as well as BBB repair following stroke." (PMID 33031376, 2020).
breast cancer (7 papers, 2012 to 2026). A primary or metastatic malignant neoplasm involving the breast. "focused on breast cancer, finding consistent results that GDF10 hypermethylation is a common epigenetic event in breast cancer, which leads to aberrant repression of GDF10 expression." (PMID 33407592, 2021). "GDF10 was also reported to function as a tumor suppressor in epithelial cells of breast cancer and to restrict their proliferation and epithelial-mesenchymal transition." (PMID 33407592, 2021). "Here, we set out to investigate the therapeutic potential of GDF10 in the 4T1.2 mouse model of breast cancer metastasis and in the C-26 mouse model of cancer cachexia, hypothesizing that GDF10 would ameliorate both metastatic and cachectic disease pathology." (PMID 42111348, 2026). "Gdf10 has been reported to act as a tumor suppressor in mammary epithelial cells that limits proliferation and suppresses epithelial-mesenchymal transition in breast cancer via upregulation of Smad7." (PMID 34104113, 2021).
Obesity (7 papers, 2018 to 2025). Accumulation of substantial excess body fat. "Future studies should aim to include a wider age range in a larger and more diverse cohort, to validate and expand upon the association between plasma GDF10 levels and obesity, as measured by BMI." (PMID 38245533, 2024). "A comprehensive understanding of the mechanisms underlying GDF10 secretion and its impact on obesity will potentially identify novel targets for interventions aimed at mitigating the adverse effects of childhood obesity." (PMID 38245533, 2024). "This study not only supports previous mouse data but is the first to report that lower levels of GDF10 is associated with childhood obesity, providing an important human connection for the relevance of GDF10 in obesity." (PMID 38245533, 2024). "Further research is needed to elucidate the regulation of GDF10 secretion and/or the causal or consequent relationship between GDF10 and obesity in humans." (PMID 37529611, 2023). "Understanding the mechanistic role of GDF10 secretion in obesity is of paramount importance as it offers valuable insights into the underlying processes involved in adiposity regulation." (PMID 38245533, 2024). "This study not only supports previous mouse data but is the first to reinforce the notion that lower levels of GDF10 is associated with increased BMI in childhood, providing an important human connection for the relevance of GDF10 in obesity." (PMID 38245533, 2024). "We and others also demonstrated that GDF10−/− mice develop severe hepatic fibrosis and lipid accumulation, whereas mice with adipose-specific overexpression of BMP-3b were protected against diet-induced obesity." (PMID 39307303, 2024). "Previous studies report diminished circulating GDF10 levels contribute to obesity and hepatic steatosis in mice." (PMID 38245533, 2024). "Further studies targeting GDF10 would provide new insight into the development of anti-obesity drugs." (PMID 37529611, 2023). "In our study, we found increased serum GDF10 concentration in participants with obesity, consistent with the results of the two studies performed on mice." (PMID 37529611, 2023). "In a previous study, GDF10 expression was found to be higher in the mesenteric adipose tissue of diet-induced obesity mice than in control mice." (PMID 37529611, 2023). "It has been shown that overexpressing GDF10 reduces obesity in mice and regulates lipid metabolism." (PMID 41227476, 2025). "This study supports the hypothesis that children with obesity display lower plasma levels of GDF10, which correlates with elevated cholesterol levels." (PMID 38245533, 2024). "Further research is warranted to elucidate the causal relationship between GDF10-mediated inhibition of PPARγ and cholesterol metabolism independent of obesity." (PMID 38245533, 2024). "Serum GDF10 concentration was high in patients with obesity." (PMID 37529611, 2023). "Furthermore, serum GDF10 concentration was higher in participants with obesity." (PMID 37529611, 2023). "Therefore, GDF10 may be a SAT-derived adipokine related to obesity." (PMID 37529611, 2023). "Therefore, GDF10 could be an adipokine related to the pathophysiology of obesity." (PMID 37529611, 2023). "Therefore, GDF10 could be a SAT-derived protein related to obesity." (PMID 37529611, 2023).
oral squamous cell carcinoma (7 papers, 2019 to 2025). "Studies have demonstrated that GDF10 expression is an independent prognostic factor for OS of patients with oral squamous cell carcinoma." (PMID 37868033, 2023). "A prior study has unveiled that GDF-10 through interaction with the transcription factor RUNX family transcription factor 2 can activate the TGFβRI/Smad3/ERK pathway in oral squamous cell carcinoma cells." (PMID 36714584, 2022). "Abnormal expression of lncRNA LOC100506114 in oral squamous cell carcinoma (OSCC) induced normal fibroblasts (NF) to transform into CAF by upregulating growth differentiation factor 10 (GDF10) expression and secretion." (PMID 33657265, 2022). "Functional experiments in oral squamous cell carcinoma unraveled that overexpression of GDF10, triggered by type III TGF-β receptor via the TGF-β-SMAD2/3 signaling pathway, resulted in appreciable inhibition in cell proliferation, migration and invasion." (PMID 33407592, 2021). "Examples include the high expression of LOC100506114 enhancing GDF10 secretion to promote oral squamous cell carcinoma metastasis, LINC00152 enhancing CXCL-11 secretion to promote liver cancer metastasis, and NORAD enhancing IL-33 secretion to promote gastric cancer metastasis." (PMID 39717771, 2024). "A parallel can be drawn with oral squamous cell carcinoma, where high expression levels of LOC100506114 intensify the secretion of the GDF10 protein into tumor cells." (PMID 39717771, 2024). "Similarly, the interaction between GDF10 and TGFBR3 regulates epithelial mesenchymal transition and tumor cell resistance through SMAD2/3 pathway in oral squamous cell carcinoma." (PMID 36714584, 2022). "Interestingly, GDF10 expression is induced by TGF-β-SMAD2/3 signaling after activation of TGFBR3, and its expression was shown to suppress survival, migration, invasion, and epithelial-mesenchymal transition (EMT) in oral squamous cell carcinoma cells." (PMID 31147529, 2019).
sarcopenia (4 papers, 2021 to 2025). Progressive decline in muscle mass due to aging which results in decreased functional capacity of muscles. "Similarly, the administration of GDF10 in aged mice reversed sarcopenia; pointing to the importance of GDF10 in muscle repair." (PMID 39307303, 2024).
fibrosis (3 papers, 2024 to 2025). the formation of excess fibrous connective tissue in an organ or tissue in a reparative or reactive process. "CCl4‐induced fibrosis model mice were treated with vehicle or GDF10‐Fc (0.01 mg kg−1 or 0.1 mg kg−1)." (PMID 40125634, 2025). "Importantly, GDF10 expression was significantly elevated in human metabolic liver disease and fibrosis samples, showing strong correlation with classic fibrosis markers (ACTA2, COL1A1)." (PMID 41281741, 2025). "To further confirm the metabolic-independent anti-fibrotic effects of GDF10, we compared Gdf10-OE mice with wild-type (WT) littermates in both CCl4- and HFMCD diet-induced fibrosis models." (PMID 41281741, 2025).
lung adenocarcinoma (3 papers, 2021 to 2025). A carcinoma that arises from the lung and is characterized by the presence of malignant glandular epithelial cells. "Among eight deBMPs/BMPRs, only BMP5 (HR: 0.59, 95% CI: 0.44–0.79, p: 4e-04 < 0.001) and GDF10 (HR: 0.74, 95% CI: 0.56–0.99, p: 0.0444 < 0.05) had prognostic value, and the higher expression of both indicated a better prognosis in lung adenocarcinoma." (PMID 34745928, 2021). "According to the immune staining intensity comparisons provided by the HPA database, the expression levels of FABP4, GDF10, and LTBP4 were higher in normal samples, while the expression level of CBLC was higher in lung adenocarcinoma samples." (PMID 40766337, 2025). "The results from the Kaplan–Meier plotter from 719 patients with lung adenocarcinoma also supported the prognostic value of BMP5 (HR: 0.48, 95% CI: 0.38–0.61, p: 9e-10 < 0.001) and GDF10 (HR: 0.73, 95% CI: 0.57–0.92, p: 0.0085 < 0.001) from TCGA-LUAD." (PMID 34745928, 2021). "We screened and verified four differentially expressed BMPs (BMP2, BMP5, BMP6, and GDF10) and one BMPR (ACVRL1), which all were downregulated in lung adenocarcinoma tissues." (PMID 34745928, 2021). "BMP2, BMP5, BMP6, GDF10, and ACVRL1 were verified as downregulated in lung adenocarcinoma." (PMID 34745928, 2021).
dyslipidemia (2 papers, 2021 to 2024). "GDF10’s protective role against dyslipidemia and hypercholesterolemia may be attributed to its inhibitory effect on PPARγ as previously shown." (PMID 38245533, 2024).
glioma (2 papers, 2022 to 2023). A benign or malignant brain and spinal cord tumor that arises from glial cells (astrocytes, oligodendrocytes, ependymal cells). "However, the expression levels of BMP2 and GDF10 were significantly positively correlated with the overall survival in glioma patients, which is inconsistent with the previous findings, suggesting that TGF-β family genes have complex regulatory functions in gliomas." (PMID 37867596, 2023).
Hepatic steatosis (2 papers, 2023 to 2024). Steatosis is a term used to denote lipid accumulation within hepatocytes. "Furthermore, circulating GDF10 levels were increased in mice with diet-induced hepatic steatosis." (PMID 37529611, 2023).